RYBP (RING1 and YY1 binding protein)
Diseases named in the same sentence as RYBP in open-access papers (continued):
Sharing a sentence is not in itself a finding about the gene and the disease.
tumor (22 papers, 2009 to 2026). "RYBP exerts tumor-specific cell killing effects, but the underlying mechanism has not been fully investigated." (PMID 25344099, 2014). "To evaluate the associations between the RYBP level and the tumor biology, we compared the clinicopathological features with the RYBP expression." (PMID 25344099, 2014). "To further validate whether virus-mediated delivery of RYBP can lead to anti-tumor effects, we generated a replication-deficient adenovirus driving the expression of RYBP (AdRYBP), and infected the HCC cells." (PMID 25344099, 2014). "In this work, we have unambiguously demonstrated a direct association between RYBP and PKP1, two proteins separately known to be involved in several types of tumor processes." (PMID 38785968, 2024). "In the context of the current knowledge of the biological pathways both proteins participate in, we propose a possible novel role for RYBP as a rescuer in some tumor cells with a high content of PKP1." (PMID 38785968, 2024). "PKP1 promotes cancer cell survival and metastasis via cluster formation in the circulatory system and, as it happens with RYBP, it has been reported to be both an oncogene and a tumor suppressor." (PMID 38785968, 2024). "Although RYBP and apoptin were found to interact and exert selective tumor killing, overexpression of RYBP was shown to induce apoptin translocation back to cytosol; similar to the effect of ATM inhibition." (PMID 36233063, 2022). "Our data indicated tumor suppressor activity of RYBP in HL which thereby contributed to elevated TLX2 expression." (PMID 33539429, 2021). "KLF4 also directly binds to the promoter of the gene coding for Ring1- and YY1-binding protein (RYBP), a tumor suppressor, and positively regulates its expression." (PMID 33266506, 2020). "Novak and coworkers demonstrated that adenoviral vectors expressing RYBP inhibited proliferation of tumour cells by inducing apoptosis, either alone or in combination with TNF‐α and etoposide, thus implicating RYBP as a therapeutic target in cancer." (PMID 29383875, 2018). "Third, somatic mutations have been reported across a range of human tumor types in several genes within the locus (FOXP1, RYBP, SHQ1)." (PMID 29057879, 2017). "Ring1 and YY1 binding protein (RYBP) induced tumour cell apoptosis by activating the activator protein 1 (AP-1) signalling pathway." (PMID 29066842, 2017). "The RybP protein, which is involved in important processes like development, apoptosis, tumor suppression, and innate immunity, was identified as an OrfX interacting partner." (PMID 29089430, 2017). "In our initial study with patient primary tumor tissue samples, we found that the RYBP level is reduced in human lung and liver cancer tissues compared to the corresponding normal tissues." (PMID 25344099, 2014). "To investigate the mechanism(s) by which RYBP reduces tumor growth and sensitizes HCC tumors to cisplatin, we further evaluated the expression levels of the various apoptosis- and metastasis-related proteins in vivo." (PMID 25344099, 2014). "We found that 378 (94.5%) HCC cases had positive tumor cell RYBP expression, with varied intensities." (PMID 25344099, 2014). "The effects of RYBP on HCC tumor growth and metastasis and chemosensitivity were determined both in vitro and in vivo." (PMID 25344099, 2014). "We first found that RYBP was downregulated in human HCC cell lines and tumor specimens and that RYBP was an independent predictor of survival in patients with HCC." (PMID 25344099, 2014). "In a multivariate analysis, the tumor RYBP status was defined as an independent prognostic factor for both the RFS and OS." (PMID 25344099, 2014). "Analysis of RYBP expression in tumors revealed dosage alterations in multiple tumor types." (PMID 39604829, 2024).
tumor (continued). "Our findings could be of importance to understand how cancer development or even the EMT mechanism can be regulated in the cell; in fact, we hypothesize that RYBP could act as a rescuer in the presence of a large amount of PKP1 in some types of tumor cells." (PMID 38785968, 2024). "Infection with adenovirus-RYBP can promote apoptosis and inhibit the proliferation of tumor cells." (PMID 34845670, 2022). "As a binding protein of RING1 and YY1, RYBP can exert a tumor suppressor effect and a good prognostic factor may depend on the role of RING1." (PMID 33634028, 2020). "Thus, further investigations of the regulation and function of RYBP in different tumour types will provide a greater understanding of the fundamental roles of RYBP in carcinogenesis and cancer progression." (PMID 29383875, 2018). "EIF4E3 falls in between FOXP1 and RYBP, and is itself a purported tumor suppressor." (PMID 25155515, 2014). "As a result of the interaction between YY1 and RYBP, the role of RYBP cannot be clearly explained, and some studies suggest that RYBP may support tumor progression by stabilizing PRC1 and repressing tumor suppressor genes, and its function seems dependent on the cellular context." (PMID 40867231, 2025). "Thus, RYBP can work both as a tumor suppressor and as an oncogene." (PMID 38785968, 2024). "Besides its role in neural development, the function of RYBP has been investigated during haematopoetic, cardiac and germ cell development and also in tumour formation, RYBP was also described as a pro-apoptotic protein and interactor of procaspase-8 and DEDD via a non-epistatic mechanism." (PMID 35149723, 2022). "Seven proteins (MYL6, AKAP9, ALDR, HS71A, KHDR1, ROA3, TAGL2) were part of both the BMI1 and RYBP chromatome, four of which (AKAP9, MYL6, ALDR and TAGL2) were identified as upregulated in IDH-wild type GBM samples versus non-tumour using TCGA datasets." (PMID 34316702, 2021). "Among these gene promoters are those involved in tumor suppression (RYBP, APEX, SST, OAS1) as well as oncogenes involved in positively aiding tumor progression (ARGH, FHX)." (PMID 23704879, 2013). "Interestingly, RYBP binds to, and upregulates, fibronectin type III and ankyrin-repeat-domain-1 protein in tumor cells to induce apoptosis via the JNK-AP1 signaling pathway." (PMID 38785968, 2024). "Unlike the CBX proteins, RYBP plays a predominantly tumor-suppressive role and is oncogenic in only a few cancers." (PMID 36076977, 2022). "Importantly, multiple accessory subunits also act as tumor suppressors, such as CBX proteins, RYBP, KDM2B, and BCOR." (PMID 36076977, 2022). "Additionally, RYBP both interacts with and up‐regulates fibronectin type III and ankyrin repeat domains 1 (FANK1) protein in tumour cells to induce apoptosis via the JNK‐AP1 signalling pathway." (PMID 29383875, 2018). "Moreover, the other genes in the deletion, EIF4E3, RYBP, PROK2, and GPR27 all mediate activities that intersect with the PI3K pathway in a potentially tumor suppressive manner." (PMID 29057879, 2017). "Furthermore, RYBP expression was induced by cisplatin, and adenovirus-mediated RYBP expression inhibited HCC tumor growth and sensitized HCC to conventional chemotherapy in vivo." (PMID 25344099, 2014). "RYBP also interacts with the viral apoptosis agonist Apoptin, and has been suggested to induce apoptosis preferentially in tumor cell lines, but not in normal fibroblasts or mesenchymal cells." (PMID 25344099, 2014). "Thus, on the basis of our results describing the binding between the two proteins, we could also hypothesize that the interaction between RYBP and PKP1 could act as a rescuer of the excess of PKP1, decreasing the amount of EMT in tumor cells." (PMID 38785968, 2024).
tumor (continued). "Since PKP1 and RYBP (i) are involved in the development of several types of cancers, (ii) can both be oncogenes and tumor suppressors, and (iii) mutually interact with the citrullinating enzyme PADI4, we hypothesized that RYBP could also be capable of binding to ARM-PKP1." (PMID 38785968, 2024).
cancer (16 papers, 2009 to 2025). A tumor composed of atypical neoplastic, often pleomorphic cells that invade other tissues. "In general terms, RYBP expression appears to be downregulated in those cancer types, and low RYBP expression is associated with poor prognosis." (PMID 38785968, 2024). "Accordingly, we propose that higher expression of RYBP will be associated with better prognosis in cancer patients." (PMID 36233063, 2022). "Of note, although the loss of the RYBP gene has been reported in several human cancers, these reports are very preliminary results in nature." (PMID 25344099, 2014). "Finally, RYBP generally localizes at SEs in both in vitro cell lines and in vivo tissue-derived cells, dysfunction of RYBP is associated with various cancers and developmental diseases." (PMID 39604829, 2024). "Dysfunction of RYBP is associated with various cancers and developmental disorders." (PMID 39604829, 2024). "Moreover, the low expression of RYBP was also associated with poor prognosis in these patients with cancer." (PMID 29383875, 2018). "In fact, this synergistic effect was lost in cells expressing RYBP and suggests that RYBP sensitizes cancer cells to PARP inhibitor, at least in part, by reducing ATM activity." (PMID 36233063, 2022). "This lower ATM activity was associated with sensitizing RYBP-expressing cells to PARP inhibitor and reducing cancer migration." (PMID 36233063, 2022). "Although we find a synergistic effect between PARP inhibitor and ATM inhibitor in cancer cells, this synergy is lost in cells expressing RYBP." (PMID 36233063, 2022). "We also show that overexpression of RYBP hinders cancer cell migration through, at least in part, ATM inhibition." (PMID 36233063, 2022). "Overall, our results and previous studies indicate that RYBP seems to play a role in regulating migration in different cells such as cancer cells and trophoblasts." (PMID 34845670, 2022). "Due to its ability to inhibit ATM activity, we find that RYBP sensitizes cancer cells to poly-ADP-ribose polymerase (PARP) inhibitors." (PMID 36233063, 2022). "We also plan to evaluate the potential of using RYBP as a potential biomarker for the diagnosis and prognosis of cancer, for assessing the progression of cancer, and for determining the response to therapy." (PMID 25344099, 2014). "Using in vitro and in vivo HCC models, we determined the role of RYBP in cancer cell response to chemotherapy." (PMID 25344099, 2014). "Based on these data, we hypothesized that PKP1 and RYBP could interact directly with each other, at least in some of those cancer cell lines." (PMID 38785968, 2024). "Altogether, RYBP is required for the cell fate control during development, as well as cancer cells." (PMID 39604829, 2024). "Given that RYBP is expressed in various cancer cells, we further investigated whether RYBP is also required for the maintenance of these cells." (PMID 39604829, 2024). "We provide new mechanism(s) by which RYBP expression may sensitize cancer cells to DNA damaging agents and inhibits cancer metastasis." (PMID 36233063, 2022). "Likewise, this provides additional insights into how RYBP sensitizes cancer cells to DNA damaging agents, e.g., PARP inhibitors." (PMID 36233063, 2022). "ATM inhibition by RYBP may further provide a new mechanism by which RYBP sensitizes cancer cells to DNA damage and PARP inhibitors." (PMID 36233063, 2022). "Clinically, we predict that patients with high-RYBP cancers will respond better to PARP inhibitors." (PMID 36233063, 2022). "In conclusion, we showed that cancer cells expressing high levels of RYBP have lower ATM activity." (PMID 36233063, 2022). "Reports indicated that RYBP is a multifunctional protein, which binds several transcriptional factors and components of polycomb repressive complex 1 (PRC1), and is associated with development, as well as apoptosis and cancer." (PMID 29383875, 2018).
cancer (continued). "Since the first discovery of RYBP in 1999, there has been marked progress in understanding its functions in physiological and pathological conditions, including embryonic development, apoptosis and cancer, as well as its role as a component of PRC1." (PMID 29383875, 2018). "Here, we will discuss the function of RYBP in these different types of cancer." (PMID 29383875, 2018). "Our results demonstrate that reactivating RYBP in cancer cells may provide an effective and safe therapeutic approach to HCC therapy." (PMID 25344099, 2014). "In light of the present evidence related to clinical cancer specimens and the pro-apoptotic role of RYBP, we concluded that RYBP may be a potential therapeutic target for HCC." (PMID 25344099, 2014). "Several studies have reported that BMI-1 has been shown to regulate DNA end resection and homologous recombination repair, whereas other studies have suggested that another PRC1 subunit, RYBP, could inhibit homologous recombination and sensitize cancer cells to poly ADP-ribose polymerase inhibitors." (PMID 39793896, 2025). "Thus, RYBP overexpression sensitizes cancer cells to DNA damaging agents." (PMID 36233063, 2022). "Hence, viral-mediated delivery of RYBP has been shown to induce apoptosis in a number of cancer cell lines, and could be a useful strategy for the patients with loss of this gene." (PMID 19911042, 2009). "Of note, It was revealed that the expression of most genes was generally consistent with results of TCGA cancer set, such as TRIM24, HMG20B, CBX6, IDH1, RCC1, RYBP, CBX7, and LBR." (PMID 36246611, 2022). "The results, however, suggest a potential role of RYBP in reducing ATM activity, and thus phosphorylation of Chk2, in two different cancer cell lines." (PMID 36233063, 2022). "Deletions at 3p13 (RYBP), 17q21.31, 20p13, 21q22.2, 21q22.3 and 22q13.31 and amplifications at 2q24.3 and 16p13.3 were more commonly present in ETS-positive cancers (Fisher’s exact test, p < 0.05)." (PMID 28945760, 2017). "From these samples, we identify established driver aberrations in a cancer-related gene in nearly all cases (97.7%), including driver gene fusions (TMPRSS2:ERG), driver focal deletions (PTEN, RYBP and SHQ1) and driver amplifications (AR and MYC)." (PMID 27328849, 2016). "RYBP is a key interaction partner of YY1, and it is also a component of the Polycomb repressive complex 1 (PRC1), a well-known chromatin-modifying complex that monoubiquitinates histone H2A, thus repressing gene expression during development and in cancer." (PMID 40867231, 2025). "Our findings suggest that RYBP might be a rescuer of the high expression of PKP1 in tumors, where it could decrease the epithelial–mesenchymal transition in some cancer cells." (PMID 38785968, 2024). "Last but not least, we found that cancer cells that overexpress RYBP show higher sensitivity to PARP inhibition and lower migration." (PMID 36233063, 2022). "Contrary to RYBP, inhibiting ATM activity in cancer cells sensitizes them to DNA damage." (PMID 36233063, 2022). "To test whether interaction between endogenous intact PKP1 and RYBP occurred within cells, we used cancer and non-cancer cell lines." (PMID 38785968, 2024). "Interestingly, in agreement with PRC1 purifications from cancer cell lines, the PCGF1-containing complex associates with RYBP or YAF2 but fails to integrate chromobox domain-containing (CBX) proteins that recognize H3K27me3." (PMID 23256043, 2012).
infection (8 papers, 2013 to 2024). The state of being infected such as from the introduction of a foreign agent such as serum, vaccine, antigenic substance or organism. "Strikingly, macrophages transfected with siRNA against RybP showed increased susceptibility to infection with either EGDe or the EGDeΔorfX mutant, indicating a protective role for RybP." (PMID 29089430, 2017). "Based on these results, we propose that RYBP promotes the establishment of KSHV latency following de novo infection through downregulation of the lytic cycle inducer gene RTA expression by blocking its transcription elongation." (PMID 36026503, 2022). "Based on our results we propose that RYBP uses a PRC1-independent mechanism to block KSHV RTA expression thereby promoting the establishment of KSHV latency following de novo infection." (PMID 36026503, 2022). "We found that RYBP can inhibit the transcription elongation of the lytic cycle inducer viral gene RTA during de novo infection, thereby promoting the establishment of KSHV latency." (PMID 36026503, 2022). "Taken together, these results demonstrate that while PRC1 binding is dispensable, the N-terminus of RYBP is crucial for the binding of RYBP to KSHV lytic promoters during de novo infection." (PMID 36026503, 2022). "A more-detailed analysis of the time course of expression of PGRP-LB and RYBP revealed that both were up-regulated as early as 1 h after infection in females, and both showed continuing strong expression 3 h after infection, especially in females." (PMID 34341118, 2021). "We show that in macrophages, the expression of OrfX decreases the level of RybP, which controls cellular infection." (PMID 29089430, 2017). "Collectively, these data reveal that Listeria targets RybP and evades macrophage oxidative stress for efficient infection." (PMID 29089430, 2017). "In the present study, we performed a preliminary evaluation of the therapeutic effects of RYBP by examining the effects of AdRYBP infection alone or in combination with cisplatin both in vitro and in vivo." (PMID 25344099, 2014). "Additionally, we found that the binding of RYBP and its effect on viral chromatin during de novo infection is PRC1-independent." (PMID 36026503, 2022). "Here, we identified RYBP as a novel repressor of the KSHV lytic cycle during primary infection." (PMID 36026503, 2022). "Taken together, these results show that RYBP does not affect the chromatinization of viral promoters, the binding of RING1B or the deposition of H2AK119ub on viral promoters supporting our notion that the effect of RYBP on KSHV gene regulation during de novo infection is PRC1-independent." (PMID 36026503, 2022). "Based on the rapid binding of RYBP to lytic viral promoters and its repressive effect on lytic gene expression at 4 hpi, we posited that RYBP binding to viral promoters is required for reducing viral gene expression during de novo infection." (PMID 36026503, 2022). "We also tested whether posttranslational modifications of RYBP play a role in its binding to viral promoters during de novo infection." (PMID 36026503, 2022). "The fact that RYBP can suppress lytic gene expression in the very early phase of infection indicates that RYBP may rapidly bind to lytic viral promoters during de novo infection." (PMID 36026503, 2022). "OrfX decreases the protein levels of RybP, which controls cellular infection." (PMID 29089430, 2017). "Having shown that OrfX decreases the level of RybP, we next asked whether OrfX affects some of the known properties of RybP upon infection." (PMID 29089430, 2017). "The expression of OrfX reduces the levels of RybP, which controls cell infection." (PMID 29089430, 2017). "The Western blotting analyses indicated that the expression changes of several apoptosis- and chemoresistance-related proteins by AdRYBP infection could be responsible for the RYBP-induced chemosensitization to cisplatin in HCC cells." (PMID 25344099, 2014).